NAT10 (N-acetyltransferase 10)
Diseases named in the same sentence as NAT10 in open-access papers (continued):
Sharing a sentence is not in itself a finding about the gene and the disease.
breast cancer (continued). "NAT10 stimulates the ac4C modification of key drug resistance genes, including breast cancer resistance protein 1 and breast cancer resistance protein in BC." (PMID 39640362, 2024). "To explore ferroptosis features in NAT10-depleted breast cancer cells, we performed a cystine uptake assay and observed a remarkable decrease in cystine levels in NAT10-depleted cancer cells, suggesting that cystine uptake could be impaired due to downregulation of SLC7A11 mRNA." (PMID 37237981, 2023). "The results consistently demonstrated that NAT10 expression in breast cancer tissues positively correlated with CD2BP2‐DT and CDK1 levels, suggesting that NAT10 acts as an upstream regulator of the CD2BP2‐DT/CDK1 signaling axis." (PMID 39976088, 2025). "We further investigated the expression of NAT10, PHGDH, and PSAT1 in the AURORA US Metastasis Project (GSE193103), a larger cohort with paired breast cancer metastases and primary tumors." (PMID 40138393, 2025). "Consistent with our findings, several recent studies reported that high expression of NAT10, PHGDH, or PSAT1 is correlated with the poor survival in breast cancer, especially the TNBC." (PMID 40138393, 2025). "In the present study, we further analyzed the correlation between NAT10, CD2BP2‐DT, and CDK1 using bioinformatic databases and IHC on TMA in breast cancer." (PMID 39976088, 2025). "We examined the effects of NAT10 knockdown on clonogenic ability in an additional TNBC cell line MDA-MB-157 and an estrogen receptor (ER)–positive breast cancer cell line T47D." (PMID 40138393, 2025). "NAT10 upregulated JunB expression by increasing ac4C modification levels on its mRNA, further up-regulated LDHA expression and facilitated glycolysis in breast cancer." (PMID 40588654, 2025). "Collectively, these results showed that NAT10 and its downstream factors PHGDH/PSAT1 are crucial for the proliferation of metastatic breast cancer cells in the serine/glycine-limited environment." (PMID 40138393, 2025). "NAT10 directly interacts with PARP1, promoting the acetylation of PARP1 transcripts, conferring resistance to platinum‐based drugs, regulating the breast cancer EMT process, and promoting doxorubicin resistance." (PMID 39764566, 2025). "Similarly, in BC, NAT10, through mediating multidrug resistance protein 1 (MDR1), and breast cancer resistance protein (BCRP), promotes tumor progression." (PMID 41316475, 2025). "For example, NAT10 promotes a mediator for DNA damage checkpoint activation, MORC2 K767Ac, and thus is considered a promising target for sensitizing breast cancer cells to DNA-damaging chemotherapy and radiotherapy." (PMID 39246323, 2024). "The study further unveiled that NAT10 acetylates the mRNA of multidrug resistance protein 1 (MDR1) and breast cancer resistance protein (BCRP), leading to increased expression levels that drive breast cancer progression." (PMID 39969189, 2025). "We found that NAT10 knockout and treatment with remodelin markedly inhibited HR efficiency in the breast cancer DR-GFP cell model but not NHEJ efficiency in the EJ5-GFP cell model." (PMID 40606759, 2025). "In addition to bone metastasis, we revisited our previous screening results of breast cancer lung metastasis and found that 231-LM2 cells with NAT10 ablation was significantly dropped out in the lungs." (PMID 40138393, 2025). "Similarly, it has been reported that NAT10 is positively correlated with ERS in acute myeloid leukemia and that high expression of NAT10 induces platinum-based drug resistance in breast cancer." (PMID 36765042, 2023). "We transfected three breast cancer cell lines, namely, MCF7, T47D, and MDA-MB-468 with NAT10 siRNA." (PMID 37237981, 2023). "To explore the expression of NAT10 in cell lines, we checked the human protein atlas; among the most highly expressed cell line in solid tumours are HeLa and MCF7, which are cell lines of cervical cancer and breast cancer, respectively." (PMID 36149760, 2022).
breast cancer (continued). "NAT10-mediated acetylation of MORC2 could force the cell to pass through the G2 checkpoint and confer resistance to DNA-damaging treatments in a breast cancer study." (PMID 34362389, 2021). "Moreover, using the CPTAC dataset, the total protein of NAT10 is higher expressed in the primary tumor of clear cell RCC, breast cancer, colon cancer, LUAD, ovarian cancer and UCEC than in normal tissues." (PMID 34094911, 2021). "Here, we show that, mechanistically, NAT10 regulates 3-phosphoglycerate dehydrogenase (PHGDH) and phosphoserine aminotransferase 1 (PSAT1) via its RNA helicase domain to support the proliferation of metastatic breast cancer cells in the serine/glycine-limited brain microenvironment." (PMID 40138393, 2025). "Mechanistic studies indicated that NAT10 directly binds to the transcripts of ABC transporter, multidrug resistance protein 1, and breast cancer resistance protein, regulating their RNA acetylation levels, maintaining their stability, and promoting breast cancer cell drug resistance and progression." (PMID 39764566, 2025). "Based on the available researches, it emerges that subnuclear localization of NAT10-specifically whether it resides in the nucleolus versus the nucleoplasm-determines cellular progression outcomes upon the presence or absence of DNA damage in breast cancer." (PMID 40588654, 2025).
hepatocellular carcinoma (30 papers, 2017 to 2026). A malignant tumor that arises from hepatocytes. "NAT10 was reported to be overexpressed in acute myeloid leukemia and hepatocellular carcinoma and is associated with decreased survival." (PMID 36609449, 2023). "NAT10 expression is notably higher in cancer tissues than in normal tissues, with elevated levels linked to poor prognostic outcomes in head and neck squamous cell carcinoma, hepatocellular carcinoma, and pancreatic cancer." (PMID 40597017, 2025). "In hepatocellular carcinoma, NAT10 activates the endoplasmic reticulum stress axis while concurrently upregulating ac4C modification levels of HSP90AA1 mRNA, thereby increasing HSP90AA1 protein expression." (PMID 40881352, 2025). "NAT10 and RNA N4‐acetylcytidine modification have attracted increasing interest in hepatocellular carcinoma (HCC) research." (PMID 41476650, 2025). "NAT10 similarly facilitates metastasis in cervical cancer and hepatocellular carcinoma through regulation of key EMT-related proteins." (PMID 40881352, 2025). "For example, the deletion of the NAT10 nuclear localization signal promotes the migration and invasion of hepatocellular carcinoma cells." (PMID 38169284, 2024). "NAT10 dysregulation has been observed in diseases such as Hutchinson‐Gilford progeria syndrome and some cancer types, including colorectal, hepatocellular carcinoma, pancreatic cancer and melanoma." (PMID 38826095, 2024). "NAT10 mediates HSP90AA1 ac4C acetylation to promote endoplasmic reticulum stress‐mediated hepatocellular carcinoma metastasis and lenvatinib resistance." (PMID 39640362, 2024). "In this study, two potential regulatory targets of NAT10 obtained through the ERS process of hepatoma cells screened by acRIP-Seq showed ac4C modification in the CDS region of mRNA." (PMID 36765042, 2023). "In a study on hepatocellular carcinoma, NAT10 expression was significantly upregulated in cancerous tissues, and its expression level was negatively correlated with the OS of patients, suggesting that it is an oncogene." (PMID 36339718, 2022). "N-Acetyltransferase 10 (NAT10) has been reported to be expressed at high levels in hepatocellular carcinoma (HCC); however, its role in chemoresistance is unclear." (PMID 31354912, 2019). "To determine the significance of NAT10 in hepatocellular carcinomas, we performed immunoblotting on human HCC tissues and their matched noncancerous tissues." (PMID 28859621, 2017). "Moreover, altered subcellular localization of NAT10 was shown to significantly enhance the invasive and migratory abilities of hepatocellular carcinoma cells." (PMID 39764566, 2025). "Furthermore, NAT10’s lysine acetyltransferase activity contributes to chemoresistance in hepatocellular carcinoma, NAT10 acetylates ACLY to boost nuclear acetyl-CoA production, enabling transcriptional activation of drug resistance genes." (PMID 40588654, 2025).
hepatocellular carcinoma (continued). "In addition, NAT10 is highly overexpressed in multiple tumor types, including melanoma, and overexpression of NAT10 correlates with worse outcomes in patients with hepatocellular carcinoma." (PMID 28880216, 2017). "Moreover, the upregulation of NAT10 was observed in chemo-resistant hepatocellular carcinoma." (PMID 40588654, 2025). "Similarly, NAT10 induced doxorubicin resistance in hepatocellular carcinoma by promoting EMT." (PMID 40606759, 2025). "In addition, NAT10 can specifically upregulate the expression of the nucleic acid acetyl coenzyme A (acetyl-CoA) to drive chemoresistance in hepatocellular carcinoma through the acetylation of ATP citrate lyase (ACLY) at K468, and K468 is required for the nuclear localization of ACLY." (PMID 41316475, 2025). "NAT10 has been found upregulated in hepatocellular carcinoma (HCC), ovarian cancer and AML, and correlates with poor survival of patients." (PMID 32241281, 2020). "High NAT10 expression levels have been observed in hepatocellular carcinoma (HCC) tissues compared with normal tissues, with increased NAT10 expression patterns predicting lower patient survival rates." (PMID 39817252, 2025). "Although studies have shown that upregulation of NAT10 promotes EMT, thereby promoting metastasis in hepatocellular carcinoma, its role in kidney cancer, especially ccRCC, is still poorly understood." (PMID 41189569, 2025). "In hepatocellular carcinoma (HCC), the intact nuclear localization signals (NLSs) of NAT10 span residues 68–75 and 989–1018." (PMID 40881352, 2025). "NAT10 is highly expressed in hepatocellular carcinoma (HCC) cell lines." (PMID 39640362, 2024). "NAT10 upregulates the modification level of HSP90 AA1 mRNA ac4C, upregulating the expression of HSP90 AA1, which further promoting the metastasis of endoplasmic reticulum stress hepatoma cells and the resistance to apoptosis of lenvatinib." (PMID 40588654, 2025). "Additionally, NAT10 knockdown was found to significantly upregulate the expression of the EMT marker cadherin 1 (E‐cadherin) and downregulate vimentin expression in hepatocellular carcinoma cells, inhibiting invasion and migration in vitro." (PMID 39764566, 2025). "NAT10 mRNA levels have also been found to be elevated in hepatocellular carcinoma (HCC) in comparison with non-cancerous tissues." (PMID 31491951, 2019). "This study demonstrates that elevated N‐acetyltransferase 10 (NAT10) expression stabilizes SMAD3 mRNA through ac4C modification, promoting the progression of hepatocellular carcinoma (HCC)." (PMID 41476650, 2025). "NAT10 could upregulate the modification level of HSP90AA1 mRNA ac4C, maintain the stability of HSP90AA1, and upregulate the expression of HSP90AA1, which further promotes the metastasis of ERS hepatoma cells and the resistance to apoptosis of Lenvatinib." (PMID 36765042, 2023).
colon cancer (20 papers, 2021 to 2025). "NAT10 expression was significantly elevated in tumor tissues and was associated with shorter survival in colon cancer patients." (PMID 38243170, 2024). "However, we did not observe a significant association between the expression of NAT10 and PD-L1 in patients with colon cancer." (PMID 38243170, 2024). "In summary, NAT10 expression is up-regulated in colon cancer and is associated with poor prognosis." (PMID 38233930, 2024). "Furthermore, high expression of NAT10 was linked to late clinical stage in colon cancer." (PMID 38243170, 2024). "The inhibitory effect of remodelin on NAT10 can improve the efficacy of chemotherapy and hinder colon cancer progression." (PMID 40606759, 2025). "NAT10 can also modify ferroptosis suppressor protein 1 (FSP1) mRNA by ac4C in colon cancer cells, which positively affects FSP1 mRNA stability and expression patterns." (PMID 39817252, 2025). "Taken together, this study demonstrated that emodin inhibited the tumor growth of colon cancer by suppressing glycolysis in tumor cells through inhibiting NAT10-mediated ac4C modification of PGK1." (PMID 41426311, 2025). "In conclusion, we demonstrated that NAT10 overexpression restored cell proliferation and glycolysis inhibited by emodin in colon cancer cells." (PMID 41426311, 2025). "Collectively, these results demonstrated that emodin suppressed ac4C modification by inhibiting NAT10 mRNA expression in colon cancer cells." (PMID 41426311, 2025). "Our results demonstrated that upregulation of NAT10 expression in colon cancer cells partially restored the cell proliferation and glycolysis that were inhibited by emodin." (PMID 41426311, 2025). "Results showed that emodin inhibited glycolysis in colon cancer cells in a dose-dependent manner, and suppressed the ac4C levels and NAT10 expression of cells." (PMID 41426311, 2025). "Compelling evidence suggesting that NAT10 plays a crucial role in the pathogenesis of various cancers by modulating glycolysis and has been shown to facilitate colon cancer progression through the inhibition of ferroptosis." (PMID 41426311, 2025). "Mechanistically, NAT10 promotes glycolysis of colon cancer cells by stabilizing PGK1 expression through enhancing ac4C modification on PGK1." (PMID 41426311, 2025). "Next, rescue experiments were performed to determine the role of NAT10 in glycolysis in colon cancer cells." (PMID 41426311, 2025). "In conclusion, these results demonstrated that cell proliferation and glycolysis of colon cancer cells inhibited by NAT10 knockdown was partially restored by PGK1 overexpression." (PMID 41426311, 2025). "In colon cancer, NAT10 is highly expressed, and previous studies have revealed that NAT10 promotes colon cancer progression by suppressing ferroptosis." (PMID 41426311, 2025). "In colon cancer, NAT10 stabilizes KIF23 mRNA by binding to its 3′UTR and enhancing ac4C modification." (PMID 40881352, 2025). "Immunohistochemistry analysis showed that NAT10 protein expression levels were significantly increased in colon cancer cells and accumulated in the nucleus." (PMID 39817252, 2025). "For instance, NAT10 promotes colon cancer development by regulating mRNA stability and FSP1 expression, thus becoming a new prognostic and therapeutic target." (PMID 38233839, 2024). "To summarize, NAT10 catalyzes ac4C formation in FSP1 mRNA to enhance its stability in colon cancer cells, increasing FSP1 expression." (PMID 38233930, 2024). "Recent studies have demonstrated that NAT10 plays a pivotal role in the development of colon cancer by affecting the stability of FSP1 mRNA and ferroptosis, underscoring its potential as a new prognostic and therapeutic target for colon cancer." (PMID 38233839, 2024). "Other studies have shown that NAT10 promotes the proliferation of colon cancer cells, and the mechanism that enhances the progression of colon cancer cells is active in the G0/G1 to G2/M phase of the cell cycle." (PMID 38233930, 2024).